BRCA1 (BRCA1 DNA repair associated)
Diseases named in the same sentence as BRCA1 in open-access papers (continued):
Sharing a sentence is not in itself a finding about the gene and the disease.
cancer (continued). "Since DNA repair mechanisms are of great interest in cancer research, it is not surprising that some of the most studied genes for cancer treatment, such as BRCA1 and RAD51, have an equally high number of reports showing miRNA-mediated regulation of these genes." (PMID 35328651, 2022). "While reversion mutations arise in all BRCA-associated cancer types, here we show that reversion mutations arising post-platinum in non-BRCA associated histologies, while rare, may indicate BRCA1/2 mediated tumorigenesis." (PMID 36418296, 2022). "Epithelial cell adhesion molecule (EpCAM)high integrin subunit alpha 6 (CD49f)+ luminal progenitors (LPs) and EpCAMlow/−CD49f+ basal cells (BCs) were isolated from reduction mammoplasty samples from 3 cancer-free non-carriers or prophylactic mastectomies obtained from 3 BRCA1-mutant donors." (PMID 35459234, 2022). "Interestingly, RAD21 expression correlated with shorter survival in BRCA2 (p = 0.006) and BRCAX (p = 0.008), but not BRCA1 cancers (p = 0.713)." (PMID 35740618, 2022). "Even if BRCA1/2 remain the highly penetrant genes, some evidences are accumulating, especially regarding other genes involved in DNA repair mechanisms, so that, a couple of years ago, the NCCN guidelines for hereditary cancers have been updated to include their analysis." (PMID 36035419, 2022). "Of patients who did not have a positive family history of any cancer (n = 487), 57 deleterious variants were detected in 54 patients, including BRCA2 (40.4%, 23/57), BRCA1 (22.8%, 13/57), PALB2 (10.5%, 6/57), NBN (5.3%, 3/57), MRE11A (5.3%, 3/57) and other genes (15.8%, 9/57)." (PMID 36232564, 2022). "While prevalences for ATM, BRCA1, BRCA2, and PALB2 in this study are consistent with prevalences observed in the literature, we calculated that as many as 1.22% of individuals in both cohorts unselected for personal or family history of cancer harbored GPV in CHEK2." (PMID 35805029, 2022). "However, in our Cohort II, patients with pathogenic BRCA1/2 mutations didn’t show longer PFS and both cancer stage and the level of residual tumor were not significant factors in the Cox multivariate analysis." (PMID 35578198, 2022). "The rate of PrCa in BRCA1 variant carriers (8.6%) was twice that of BRCA2 variant carriers (3.8%), screening all men using annual PSA and DRE (neither PSA screening threshold or cancer characteristics reported)." (PMID 33486571, 2022). "One of the most interesting results of the study highlights that men are also driven by concern for their children, regardless of family history of BRCA1/2 related cancers and age, and the presence of children is significantly associated with the more concrete formation of intention." (PMID 35303741, 2022). "Thus, the higher level of BRCA1 and BRCA2 mRNA observed in tumors may result from the proliferation status of cancer cells." (PMID 35203410, 2022). "However, not all HRD-associated BCs have a genetic defect in either BRCA1 or BRCA2, therefore identifying the HRD phenotype itself among cancers is crucial." (PMID 35159019, 2022). "However, except for the BRCA1 group, no statistical difference was noted among patients, mainly because of the low numbers of cancers (all p > 0.05)." (PMID 35681739, 2022). "However, cost is seemingly not the only barrier to testing, as BRCA1/2 testing remains underutilized in cancer patients, even for those with insurance coverage and access to specialty genetic services." (PMID 35205643, 2022). "We present the results of multigene panel testing among individuals who tested negative for BRCA1/2 in a multi‐ethnic, large, urban comprehensive cancer center genetics clinic including individuals seen in both urban and other sites across the state of Michigan." (PMID 35040284, 2022).
cancer (continued). "However, the prevalence of BRCA1/2 large genomic rearrangements (LGRs) in Chinese cancer patients has not been well revealed partially due to technical difficulties in LGR detection." (PMID 36147908, 2022). "BRCA1 or BRCA2 negative cancers cannot use the HR pathway to repair DNA DSBs." (PMID 33926008, 2021). "Similar to BRCA1/2 playing a crucial role in the HRR process, the satisfactory performance of the CNV of 8q24.2 in predicting pan-cancer HRD led us to speculate that some genes on this fragment may influence the HRD status of patients through an intrinsic mechanism." (PMID 34976815, 2021). "Indeed, a recent study has shown that BRCA1 and BRCA2 variants are rare (<0.2%) in the non-cancer FC population with no personal or family history of cancer relative to cancer cases." (PMID 34298626, 2021). "The DNA double-strand breaks induced by oxidative estrogen metabolites could not be repaired without Brca1, thus resulting in genomic instability and cancer development." (PMID 33498875, 2021). "When including the discovery OC family, there was an increased carrier frequency of c.1813C>T in BRCA1 and BRCA2 pathogenic variant negative OC families versus sporadic OC cases (P = 0.01, Fisher’s exact) and cancer-free females (3/23, 13%; OR = 5.8; 95%CI = 1.7-19; P = 0.005)." (PMID 34861889, 2021). "For example, for a variant in BRCA1/BRCA2, first, the patient with cancer may not be eligible for cancer treatments from which they would likely benefit, for example, platinum-based chemotherapy and/or poly ADP ribose polymerase (PARP) inhibitors." (PMID 33208383, 2021). "Besides somatic mutations, BRCA1 promoter hypermethylation and decreased BRCA1 expression, by epigenetic silencing or gene depletion, can also render a dysfunctional BRCA1 pathway in non-hereditary cancers." (PMID 34298653, 2021). "Moreover, prior studies have demonstrated that inhibitors of BET, CDK1, HDAC, Protease, PI3K, and VEGFR could all decrease BRCA1 and other HRR factors at the protein level, thereby increasing the sensitivity of the cancer cell lines to PARP inhibition." (PMID 33589588, 2021). "Recent clinical evidence, however, shows that PARPi can be effective as cancer therapeutics regardless of BRCA1/2 or HRD status, suggesting that a broader population of patients might benefit from PARPi therapy." (PMID 33487630, 2021). "Therefore, BRCA1 mutations in the coding region are not involved in the development of sporadic cancers, and alternative inactivating mechanisms, such as promoter mutation and DNA hypermethylation, may be involved in the dysregulation of the BRCA1 gene in sporadic human cancers." (PMID 34926299, 2021). "We previously reported a rare BRCA1 and BRCA2 pathogenic variant negative OC family (F1528) in a study of the histopathology of OC and BRCA1 and BRCA2 pathogenic variant carrier status of FC cancer families." (PMID 34861889, 2021). "Preclinical evidence from different cancers (including OC) showed that hypomethylating agents can re-sensitize cancer cells to platinum in vitro and in murine models by restoring tumor-suppressor genes expression (such as RASSF1A, BRCA1, DAPK, OPCML, and hSulf-1)." (PMID 34948446, 2021). "The efficacy of PARP inhibitors in cancer treatment is not restricted to BRCA1/2 mutant sufferers." (PMID 34054126, 2021). "We then estimated how much the posterior probability is affected by whether or not clinical information such as pathologic profiles or personal/family cancer history exists, with specific focus on BRCA2, c.7522G>A, p.(Gly2508Ser) and BRCA1, c.5339T>C, p.(Leu1780Pro)." (PMID 34063308, 2021).
cancer (continued). "However, among 26 men who were affected with first BC, 42% did not have any relatives with cancer (11/26; 2 BRCA1 and 9 BRCA2; P = 0.56)." (PMID 34575694, 2021). "As not all such cancer syndrome families are explained by BRCA1 and BRCA2, newly proposed gene candidates identified in other populations have been investigated for their role in conferring risk in French Canadian cancer families." (PMID 34298626, 2021). "Interestingly, the Hallmark DNA repair gene set does not include known DNA repair genes such as BRCA1 and BRCA2, arguably the most clinically relevant DNA repair genes associated with cancers." (PMID 33477315, 2021). "Although we failed to monitor BRCA1 phosphorylation in estrogen-treated murine ovarian epithelium, possibly due to antibody specificity, our data implicate that BRCA1 participates in preventing damage accumulation in both replicating and non-replicating cells in cancer tissue." (PMID 33087072, 2020). "Compensatory mechanisms of restoring fork protection in the absence of BRCA1/2 or PARP1 may be at play in PARP inhibitor-resistant cancers." (PMID 32029455, 2020). "The presence of BRCA1 germline alteration is more closely involved in HRD than that of BRCA2, and it is anticipated that BRCA-associated cancer may be differentiated even in the absence of BRCA1 germline mutation if a similar expression profile is exhibited." (PMID 32719318, 2020). "The main purpose of this review is to summarize the molecular biology associated with the representative cancer predisposition genes, BRCA1 and BRCA2, and to speculate on the missing link between normal and cancer cells." (PMID 32269964, 2020). "TIGAR is amplified in different cancer types and its down-regulation sensitizes cancer cells to PARP inhibitors through inhibition of the pentose phosphate pathway, increase in ROS and DNA damage, down-regulation of BRCA1/2 and RAD51, and induction of cellular senescence." (PMID 32029455, 2020). "These types of BRCA1/2 negative cancers are naturally sensitive to PARP inhibitors." (PMID 32194409, 2020). "However, in some cancer cells lacking BRCA1 or BRCA2, two key tumor suppressor proteins involved in DSB repair by HR, loss of PARP function leads to the accumulation of DSBs that are unrepaired or unsustainably repaired by NHEJ which results in cell death." (PMID 32526888, 2020). "It has been shown that BRCA1 and BRCA2 are involved in the repair process of DNA damage in different tissues and any reduction and/or disruption of these two proteins may lead to cancer." (PMID 32458652, 2020). "The aberrant BRCA1 promoter methylation is found in approximately one-ninth of ovarian cancer tumors and in one-fourth of breast basal-like tumors, suggesting that BRCA1 silencing is considered a leading non-genetic case of BRCA1 inactivation in sporadic wild-type BRCA cancer." (PMID 32269964, 2020). "As it has been shown that treatment with PARP inhibitor Olaparib enables to induce BRCA1 foci formation in human cancer cells, we next examined whether depletion of USP9X could affect Olaparib induced the formation of BRCA1 foci using immunofluorescent staining." (PMID 31512408, 2019). "Thus, differences in WBC subfractions between cancer patients and controls is not a likely explanation why BRCA1 methylation is increased among the patients diagnosed with HGSOC." (PMID 31225507, 2019). "In addition, we chose to use the DNA damaging agent Cisplatin to explore mTORC2 effects in response to DNA damage because it is known to preferentially induce cancer cell death when functional BRCA1 is absent." (PMID 31771139, 2019). "Importantly, SOX17 transcriptionally down-regulated DNA repair and damage response-related genes including BRCA1, BRCA2, RAD51, KU80 DNAPK, p21, SIRT1, NFAT5 and REV3L in KYSE510 radio-resistant cells to achieve the sensitization effect to anti-cancer treatment." (PMID 30777052, 2019).
cancer (continued). "PTEN, BRCA1, and BRCA2 proteins play an important role in resisting the growth of BREAST cancer, while PI3K and CCND1 proteins could improve the growth of BREAST cancer." (PMID 30792708, 2019). "It is well accepted that downregulation of BRCA1 and BRCA2 leads to PARP inhibitor sensitivity, and our data suggest that TIGAR KD induces “BRCAness” by phenocopying the gene expression pattern produced by BRCA1/2 downregulation and thereby sensitizes cancer cells to olaparib." (PMID 31508509, 2019). "We conclude that there is no cancer type in TCGA that harbors an excess of damaging germline variants in DDR or cancer-relevant genes, with the exception of the well-described predisposition syndrome genes BRCA1/2, SDHB, and RET." (PMID 30217226, 2018). "To investigate the potential transmission of methylated BRCA1 promoter from mother to daughter, we examined the BRCA1 promoter methylation status in DNA from WBC using MSP assay in a cohort of 865 female subjects (cancer-free women, n = 268; delivering women, n = 295; newborn females, n = 302)." (PMID 30049288, 2018). "Therefore, when BRCA1 is lost, the cancer cells will no longer activate the mitotic spindle checkpoint protein MAD2, and subsequent activation of the pro-apoptotic JNK pathway will cause resistance to the anti-microtubule agent." (PMID 29932172, 2018). "Importantly, TIRR mutants with altered 53BP1 Tudor binding may sensitize the BRCA1-mutant tumor cells to PARPi, indicating a therapeutic potential of TIRR in cancer treatment." (PMID 29844495, 2018). "Conversely, a lower proportion of survey responders with completed BRCA1/2 testing had no personal history of cancer (62.2% tested vs. 80.1% not tested, p < 0.01) and a family history of a cancer other than breast or ovarian (15.5% tested vs. 26.2% not tested, p < 0.01)." (PMID 29514700, 2018). "For example, the identification of synthetic lethal interactions between BRCA1 or BRCA2 tumour suppressor genes and inhibition of the PARP1 DNA repair protein has driven the clinical development and approval for use of PARP inhibitors for the treatment of cancer." (PMID 29915391, 2018). "The response observed in women with EOC lacking BRCA1/2 mutations was attributed to ‘BRCA-ness’, a molecular genetic signature in cancers equivalent to those with a BRCA1/2 mutation where other HR components were deficient by mutation or were epigenetically silenced." (PMID 27374179, 2017). "BRIP1 is a DNA-dependent ATPase and a 5′-to-3′ DNA helicase that achieves its cancer suppression function and DNA double-strand break repair through direct interaction with the highly conserved, C-terminal BRCT (BRCA1 C-Terminal domain) protein domain repeats of the tumor suppressor BRCA1." (PMID 28968953, 2017). "Interestingly, our data showed that, unlike BRCA1 mutant MDA-MB-436 and SUM149PT cancer cells, BRCA1-depleted MCF7 cancer cells were not sensitive to EEPD1 depletion." (PMID 29145865, 2017). "Indeed, whereas FL BARD1 protein acts as tumor-suppressor with and without BRCA1 interactions, aberrant splice variants of BARD1 have been detected in various cancers and have been shown to play an oncogenic role." (PMID 29292755, 2017). "Clinically, the PARP inhibitor veliparib (ABT-888; AbbVie) is being investigated in Phase three studies of several cancers including lung (NCT02264990), triple negative breast cancers (NCT02032277) and HER2 negative BRCA1/2 deficient breast cancers (NCT02163694)." (PMID 28314386, 2017). "In support of the recalcitrant nature of BRCA1-related cancers to therapy, we show the predominant expression of stem cell markers in mammospheres derived from BRCA1-defective cancer cells in contrast to the EMT markers expressed by BCSCs in a BRCA1-competent condition." (PMID 27229859, 2016).
cancer (continued). "BRCA1-KO fibroblasts treated with cancer patients’ sera displayed higher proliferation and underwent malignant transformation as opposed to wild type fibroblasts, which were not affected by exposure to cancer patients’ sera." (PMID 27179759, 2016). "Several cancer related PCGs were involved such as CDK1/2, BRCA1 and TGFBR2, suggesting that lncRNAs in the core subnetwork may mediate the tumorigenesis by competitively regulating these cancer driver genes in pan-cancers." (PMID 27580177, 2016). "Notably, vimentin staining of all the cancerous masses was negative indicating that cancer factors carried in the sera of all tested patients had integrated in the genome of the BRCA1-KO fibroblasts changing their fate permanently." (PMID 27179759, 2016). "To evaluate whether this phenotype is unique to GBM or applies to other cell types, we performed BRCA1 knockdown in 4 additional cancer and 3 non-malignant cell lines." (PMID 27845331, 2016). "This makes it difficult to conclude whether NDR-acquiring CGI promoters are more likely to be the result of a cis versus trans mechanism, but this question is central to understanding how CGI promoters for cancer driver genes like MLH1, BRCA1, and VHL become epigenetically silenced in cancer." (PMID 25747664, 2015). "Initial investigation of the frequency and co-occurrence of PPVs from a limited panel of 163 disease genes in the BRCA1/2-carrier cohort indicated that the majority of nonsynonymous PPVs in the cancer genetics clinic will be novel VUSs (not present in the ESP6500 database)." (PMID 26023681, 2015). "Consequently: (i) PARP, being part of the NHEJ machinery, functions throughout the cell cycle, and in general is overexpressed in fast-dividing cancer cells that harbour DNA breaks; but (ii) the functions of PARP and BRCA1-mediated repair overlap specifically during the DNA replication (G1/S-phase)." (PMID 26427375, 2015). "Thus, even though loss of EEPD1 results in genomic instability, EEPD1 should not be viewed as a tumor suppressor in the same sense as BRCA1 and BRCA2, two HR components that show loss of function mutations in cancer." (PMID 26684013, 2015). "WGS was performed on a series of patients from the cancer genetics clinic that included those found to have BRCA1 (n = 88) or BRCA2 (n = 88) mutations, as well as those that were not carriers of a BRCA1/2 mutation (n = 82)." (PMID 26023681, 2015). "Additionally, it has been observed that BRCA1 mislocalizes to the cytoplasm in cancer cells but not in normal cells." (PMID 26402707, 2015). "Eleven cancer related genes were found to have methylation (defined as more than 10 % methylation) in at least some of the tumours: RASSF1A (64 %), TWIST1 (61 %), CDH13 (51 %), APC (50 %), MAL (35 %), GSTP1 (30 %), WIF1 (26 %), RARβ (19 %), BRCA1 (2 %), CDKN2A (2 %) and TP73 (2 %)." (PMID 26452468, 2015). "From the BRCA1 study, differentially methylated CpGs, with false discovery rate (FDR) corrected P values, between BRCA1 mutant carriers and BRCA1 wild type samples were identified via a multivariate logistic regression that was adjusted for age, batch and the presence of cancer." (PMID 25067956, 2014). "Direct inhibition of BRCA1 and BRCA2 in tumors is generally problematic due to the wide expression of these proteins in most tissues and inhibition may lead to other issues, including cancer development in healthy tissue." (PMID 24795863, 2014). "Human and zebrafish genomes are 70% similar based on conservation of individual genes, with several cancer-associated genes found in mammals but not in the zebrafish, including BRCA1, p16 (CDKN2A), BRCA1, LIF, OSM, IL6 and PML (G.D. and J.N.B., unpublished observation)." (PMID 24973744, 2014).